METAP1 (methionyl aminopeptidase 1)
Description:
Cotranslationally removes the N-terminal methionine from nascent proteins. The N-terminal methionine is often cleaved when the second residue in the primary sequence is small and uncharged (Met-Ala-, Cys, Gly, Pro, Ser, Thr, or Val). Required for normal progression through the cell cycle.
Synonyms: KIAA0094; MetAP1A; MAP1A
Tractability: Small molecule: a drug acting on it is in phase 2 or 3 trials; a structure with a bound ligand is known; a high-quality ligand is known; it has a binding pocket of medium quality; it belongs to a druggable protein family. Antibody: the Human Protein Atlas places it where antibodies can reach. PROTAC: ubiquitination databases record sites on it; its protein half-life has been measured; a small molecule that binds it is known.
Target class: Protease; Enzyme; Metallo protease MG clan; Metallo protease; Metallo protease M24A subfamily
Gene: Protein-coding gene on chromosome 4 (98,995,359 to 99,063,443, forward strand). Ensembl gene ENSG00000164024.
Subcellular location: Cytoplasm
Subcellular location (Human Protein Atlas): Cytosol; Nucleoplasm; Plasma membrane
Pathways (Reactome):
Sensory Perception: Inactivation, recovery and regulation of the phototransduction cascade
Gene Ontology:
Molecular function: aminopeptidase activity; initiator methionyl aminopeptidase activity; protein binding; metalloaminopeptidase activity; metalloexopeptidase activity; metal ion binding
Biological process: platelet aggregation; protein maturation; regulation of translation; proteolysis
Cellular component: cytoplasm; cytosol
Genetic constraint (gnomAD): Loss-of-function variants: 14 observed, 24.96 expected, observed/expected ratio (o/e) 0.56, 90% interval 0.37 to 0.88. The upper end of that interval is the gene's LOEUF score, 0.88, which puts it in group 3 of 6, group 1 being the genes least tolerant of losing a copy. Missense variants: 240 observed, 308.28 expected, observed/expected ratio (o/e) 0.78, 90% interval 0.7 to 0.87. Synonymous variants: 122 observed, 111.08 expected, observed/expected ratio (o/e) 1.1, 90% interval 0.95 to 1.28.
Homologues: Orthologues: chimpanzee METAP1 (99% identical), macaque METAP1 (99% identical), dog METAP1 (99% identical), pig METAP1 (99% identical), mouse Metap1 (98% identical), rat Metap1 (98% identical), guinea pig METAP1 (92% identical), rabbit METAP1 (90% identical), tropical clawed frog metap1 (89% identical), zebrafish metap1 (87% identical), Drosophila melanogaster CG13630 (61% identical), Caenorhabditis elegans map-1 (60% identical). Paralogues in human: METAP1D (36% identical), XPNPEP1 (17% identical), XPNPEP2 (16% identical), PEPD (15% identical), XPNPEP3 (14% identical), PA2G4 (12% identical), METAP2 (11% identical).
Diseases named in the same sentence as METAP1 in open-access papers:
METAP1 is named in the same sentence as 25 diseases in open-access papers, as found by Europe PMC text mining. Sharing a sentence is not in itself a finding about the gene and the disease. The quoted sentences say what the papers report.
breast carcinoma (3 papers, 2022 to 2025). "In human breast cancer cells METAP1 or METAP2 knockdown in combination with BEZ treatment reduced cell growth significantly better than knockdown alone but not significantly better than PI3K-inhibitor treatment alone, comparable with shRenilla control cells." (PMID 35673573, 2022). "Our data confirmed the known tumor promoting function of Usp7 and Metap2 in murine and human breast cancer cells, postulating a new importance of Metap1 for breast cancer cell growth." (PMID 35673573, 2022). "In summary, knockdown of Metap1 or Metap2 sensitized murine and human breast cancer cells as well as human hepatocellular carcinoma and colorectal cancer to PI3K inhibition showing partly synergistic effects." (PMID 35673573, 2022). "Metap1 is known to act as tumor-promoting in cervical cancer, fibrosarcoma, and lung cancer, and we recently discovered a role for Metap1 in promoting the sensitivity of breast cancer cells to phosphoinositide 3-kinase (PI3K) inhibition." (PMID 36313646, 2022). "Knockdown of Metap1 or Metap2 alone already significantly impaired breast cancer cell growth in comparison to DMSO-only treated cells." (PMID 35673573, 2022). "In line with the known tumor promoting function of these proteases we demonstrated Usp7 and Metap2 to be important for murine and human breast cancer cell growth and discovered a role for Metap1 in this context." (PMID 35673573, 2022). "In murine breast cancer cells synergisms was also detected for combined Metap1 or Metap2 knockdown and BEZ treatment, despite for shMetap2-1." (PMID 35673573, 2022). "Synergistic effects on breast cancer cell growth were observed upon knockdown of Metap1 or Metap2 in combination with BKM EC10 and EC20 treatment in all three cell lines." (PMID 35673573, 2022). "Additionally, Metap1, Metap2 or Usp7 knockdown sensitized PyMG-TA and PyB6-TA breast cancer cells to BKM treatment in comparison to cells with unaltered protease expression." (PMID 35673573, 2022). "Here we discovered a dependency of breast cancer cells on Metap1." (PMID 35673573, 2022). "In addition, we excluded involvement of several MAPK pathway related kinases in the combinatory effect of METAP1 or METAP2 knockdown with BKM treatment in human breast cancer cells." (PMID 35673573, 2022). "In addition, small but significant changes in PI3K pathway activation were observed upon knockdown of METAP1 or METAP2 in human breast cancer cells." (PMID 35673573, 2022). "Next, we tested whether knockdown of Metap1 or Metap2 might provide synergistic effects to PI3K inhibition not only in murine breast cancer cells, but also in human MCF7-TA and MDAMB-TA cells representing luminal A-type and triple-negative breast cancers, respectively." (PMID 35673573, 2022). "Because the synergistic effects might be due to a direct link of METAPs to PI3K signaling, we analyzed the activity of the PI3K pathway by means of the phosphorylation status of three players (Akt, mTOR, S6) upon METAP1 or METAP2 knockdown in human breast cancer cells." (PMID 35673573, 2022). "Specifically, knockdown of Metap1 or Metap2 impaired MTT viability and reduced competitive cell growth in murine breast cancer cells." (PMID 35673573, 2022). "Usp7, Metap1 and Metap2 are synthetic lethal partners of simultaneous protease/PI3K inhibition, which may refine future breast cancer therapy." (PMID 35673573, 2022). "In comparison to DMSO-only treated cells, knockdown of Metap1 or Metap2 stalled murine PyB6-TA cells in G1-phase and human MDAMB-TA cells in G2-phase, thus leading to an impaired cell cycle progression to S-phase in murine and human breast cancer cells." (PMID 35673573, 2022). "Importantly, we discovered an advantage for combining Metap1, Metap2 or Usp7 knockdown with PI3K inhibition to target breast cancer cells." (PMID 35673573, 2022).
breast carcinoma (continued). "In line with our screen data, Usp7, Metap1, Metap2, and MMP17 could be validated as depletion hits in vitro, whereby targeting reduced MTT viability and competitive breast cancer cell growth." (PMID 36313646, 2022). "Knockdown of Usp7, Metap1 or Metap2 impaired MTT viability to different extent, with both breast cancer cell lines being more sensitive than non-cancerous cells." (PMID 35673573, 2022).
cervical cancer (2 papers, 2022). A primary or metastatic malignant neoplasm involving the cervix. "In contrast to Metap2, Metap1-specific inhibition is relatively rarely investigated but was shown to have anti-tumor effects in cervical cancer and fibrosarcoma cells 65, as well as in human umbilical vein endothelial cells and human lung carcinoma cells." (PMID 35673573, 2022).
alcohol use disorder (1 paper, 2025). "We identified one candidate causal protein for Parkinson’s disease (GBA1) and two for alcohol use disorder (METAP1 and ADH5) in participants of African ancestry." (PMID 40921788, 2025). "Third, we identified two candidate causal proteins specific to individuals of African ancestry in alcohol use disorder (ADH5 and METAP1) despite lower statistical power from the corresponding GWAS and reference proteogenomic data." (PMID 40921788, 2025).
autism (1 paper, 2024). Persistent deficits in social interaction and communication and interaction as well as a markedly restricted repertoire of activity and interest as well as repetitive patterns of behavior. "This was followed by the sequential expression of METAP1, a risk gene for autism and schizophrenia, along with AP3B2, a risk gene for developmental delay." (PMID 39363111, 2024).
leishmaniasis (1 paper, 2021). Infectious disease that is transmitted through the bite of hematophagous female phlebotomine sand flies. "Recently, MetAP1 inhibitors have shown promising results against Leishmania donovani, giving more evidence for the use of MetAP1 inhibitors for the treatment of Leishmaniasis." (PMID 33925369, 2021).
Prader-Willi syndrome (1 paper, 2023). "Since discovering that human MetAP2, not human MetAP1, is the molecular target of TNP-470, a potent anti-angiogenesis inhibitor, MetAP2 has become a drug target for treating cancer, obesity, Prader-Willi Syndrome (PWS), and autoimmunity." (PMID 37511988, 2023).
Zinc deficiency (1 paper, 2025). A deficiency of the essential metal Zinc; an essential cofactor for many enzymes. "For example, the amount of MetAP-1 of S. cerevisiae (Map1) is more reduced under zinc deficiency." (PMID 40985948, 2025).
cancer (6 papers, 2014 to 2025). A tumor composed of atypical neoplastic, often pleomorphic cells that invade other tissues. "We employed a panel of six fluorescently labeled CCP probes that were designed for cleavage by specific proteases implicated in cancer progression: ACE2, CATB, METAP1/2, MMP14, plasmin, and USP1516–22." (PMID 40890441, 2025). "All probes, except METAP1/2, showed significant signal differences between each cancer group (CRC, EGJC or GC) and the HC group (p-values ranging from < 0.0001 and < 0.05)." (PMID 40890441, 2025). "Studies have shown that METAP1 inhibitors have potential therapeutic benefits in the treatment of various diseases, including cancer and malaria." (PMID 37367074, 2023). "By identifying these characteristics in a patient’s cancer cells, healthcare providers can determine the potential effectiveness of METAP1 inhibitors and redox-targeted therapies in that specific individual." (PMID 37367074, 2023). "These measurements provide vital information about the role of METAP1 in cancer and the redox status of cancer cells." (PMID 37367074, 2023). "In this research, these authors identified and validated the proto-oncogene c-Src, involved in the development, growth, progression and metastasis of a number of human cancers, as a substrate for both MetAP1 and MetAP2 in vivo and in vitro." (PMID 24646945, 2014). "Therefore, METAP1 levels and redox homeostasis imbalances can serve as innovative tools to develop personalized cancer treatments." (PMID 37367074, 2023). "These enzymes have been implicated in key cancer-associated processes such as extracellular matrix degradation (MMP14, plasmin), tumor invasion and metastasis (CATB), immune regulation and signaling (USP15), and cancer-related proteolytic processing (ACE2, METAP1/2)." (PMID 40890441, 2025). "Across all six probes—targeting ACE2, CATB, METAP1/2, MMP14, plasmin, and USP15—significantly elevated protease activity was observed in cancer patients compared to healthy controls." (PMID 40890441, 2025). "Across all cancer groups, METAP1/2 consistently showed weak or negative correlations with other proteases." (PMID 40890441, 2025). "We further set out to investigate whether the synergistic effect of PI3K inhibition and Metap1 or Metap2 knockdown is transferrable to cancer cells not originating from breast malignancies." (PMID 35673573, 2022).
tumor (3 papers, 2016 to 2022). "Finally, we decided to further investigate Usp7, Metap1 and Metap2 due to most distinct effects in the first validation assays and literature postulating tumor-promoting functions of these proteases 62-73." (PMID 35673573, 2022). "We suggest that MetAP1 levels could be routinely checked in several types of tumor and used as a prognostic marker for predicting the response to treatments inhibiting MetAP2." (PMID 27542228, 2016). "We suggest that MetAP1 expression could be routinely checked in several types of tumor, as a prognostic marker for predicting the efficacy of any treatments targeting MetAP2 activity and for the fine-tuning of therapeutic strategies." (PMID 27542228, 2016).
METAP1 also shares sentences with these, for which no sentence is quoted: lung carcinoma (2 papers); acute lymphoblastic leukemia (1); breast (1); CNS tumor (1); colorectal adenocarcinoma (1); colorectal cancer (1); developmental delay (1); fibrosarcoma (1); glioma (1); hepatocellular carcinoma (1); non-Hodgkin lymphoma (1); pancreatic ductal adenocarcinoma (1); Parkinson disease (1); preeclampsia (1); schizophrenia (1); triple-negative breast carcinoma (1).